CEACAM6 (CEA cell adhesion molecule 6)
Diseases named in the same sentence as CEACAM6 in open-access papers (continued):
Sharing a sentence is not in itself a finding about the gene and the disease.
infection (13 papers, 2011 to 2025). The state of being infected such as from the introduction of a foreign agent such as serum, vaccine, antigenic substance or organism. "We found that IV infection caused: i) a progressive increase in TF antigen exposure; ii) a significant increase in mRNA level of CEACAM6 and its expression on the cell surface." (PMID 25706391, 2015). "Interestingly, AIEC bacteria were able to highly persist in the gut of mice for up to 21 days after a unique infection, with a significant higher quantity of bacteria associated with jejunal and ileal mucosa in transgenic mice expressing CEACAM6 compared to WT mice." (PMID 36172858, 2022). "Furthermore, infection of wild-type MKN28 cells by a live CagA wild-type H. pylori strain also resulted in an increase in CEACAM6 transcripts, confirming this association to be physiological and not an artifact of high levels of overexpression in the tet-inducible system." (PMID 27421133, 2016). "Infection of hypoxia-reoxygenated GECs also resulted in significantly increased CEACAM6 and NOX4-mediated ROS generation compared to normoxic GECs." (PMID 40325849, 2025). "Accordingly, temporal upregulation of CEACAM6 instead of high abundance seems to be crucial for cellular survival signaling during infection." (PMID 30973879, 2019). "Moreover, small intestinal biopsies of ETEC infected patients also demonstrated significant increases in CEACAM6 expression following infection." (PMID 36865539, 2023). "To confirm that the increase in galactose and mannose residues previously observed were related to TF and CEACAM6 antigens, whose abnormal expression has been documented in CD patients, we assessed their exposure on Caco-2 cells during IV infection at 48 hrs post plating." (PMID 25706391, 2015). "Overall the data confirm that the exposure of TF and CEACAM6 antigens observed during IV infection plays a key role in increasing bacterial adhesion to intestinal cells, but we cannot exclude that other cellular receptors could be involved." (PMID 25706391, 2015). "Interestingly, influenza virus (IV) infection has been shown to induce over-expression of CEACAM6 protein, probably via interaction with NA followed by activation of the Src/Akt signaling pathway in lung epithelial cells." (PMID 25706391, 2015). "However, ileal epithelial expression of CEACAM6 is increased by LF82 infection, as well as pro-inflammatory cytokines." (PMID 23251695, 2012). "In infection assays, loss of CEACAM6 expression did not alter the number of either glucose- or MDX-exposed LF82 adhering to Caco2 monolayers, as quantitated by colony counts or visualized by confocal microscopy." (PMID 23251695, 2012). "Enhanced expression of CEACAM6 in individuals with inflammatory bowel disease promoted by inflammatory mediators accelerates binding of AIEC, and AIEC infection of epithelial cells in vitro induces expression of multiple CEACAMs." (PMID 36865539, 2023). "Intriguingly, in vitro studies demonstrated that CEACAM6 expression is increased in cultured IECs after infection with AIEC, indicating that AIEC promotes its own colonization through induction of CEACAM6 expression in the host." (PMID 35198577, 2022). "Infection of untreated Caco-2 cells with four AIEC strains LF82, EC29, EC38, and EC47 increased CEACAM6 levels compared to control uninfected Caco-2 cells." (PMID 33538227, 2021). "The infection of Caco-2 cells with EC30 isolate has not changed the CEACAM6 level comparing to untreated cells." (PMID 33538227, 2021). "In contrast to NXF1, CEACAM6 is not directly involved in steps of RNA synthesis but seems to interact with newly synthesized viral NA proteins during infection, which activates the Src/Akt survival pathway in A549 cells as shown by Gaur and colleagues." (PMID 30973879, 2019).
infection (continued). "Over-expression of CEACAM6 in intestinal cells has been reported after stimulation with inflammatory cytokines such as Interferon (IFN)-γ and Tumor Necrosis Factor (TNF)-α, or after infection with E. coli AIEC." (PMID 25706391, 2015). "We found that adhesion index of LF82-ΔfimH mutant did not change in presence or absence of CEACAM6 antibody (15.48±7.54 and 15.73±6.80, respectively), suggesting that not only FimH adhesin could be involved in bacterial adhesion during IV infection." (PMID 25706391, 2015).
adenocarcinoma (8 papers, 2007 to 2025). A common cancer characterized by the presence of malignant glandular cells. "From this analysis, it becomes evident that CEACAM6 holds a distinct advantage, offering a broader potential application for treating adenocarcinomas within the digestive system." (PMID 38975894, 2024). "Taken together, these data indicate that pHLIP-miR-29a effectively translocated miR-29a to adenocarcinoma cells from various organs and inhibited protein expression of CEACAM6." (PMID 37684602, 2023). "We show that CEACAM6 is expressed in particular in mucin-producing, gland-forming adenocarcinomas that arise in the gastrointestinal tract, lung, and ovary." (PMID 25427744, 2015). "CEACAM6 expression is high in particular in mucin-producing, gland-forming adenocarcinomas arising in the gastrointestinal tract, ovary, and NSCLCs." (PMID 25427744, 2015). "Because a number of human adenocarcinomas express higher levels of CEACAM6 than other histologic subtypes, these results may have direct translational implications for the treatment of various human adenocarcinomas." (PMID 31474761, 2019). "Among these, adenocarcinoma expressed more CEACAM6 than squamous cancer (P < 0.001)." (PMID 17201906, 2007).
bacterial infection (3 papers, 2011 to 2018). "Considering recent evidence showing that certain CEACAM6 haplotypes modulate susceptibility to bacterial infections, we next performed a detailed haplotype analysis in our IBD cohort." (PMID 21559399, 2011). "Examination of early bacterial infection events by SIM demonstrated the clustering of CEACAM6 at the places of initial bacterial binding." (PMID 29720971, 2018). "The expression of CEACAM6 was not affected by any treatment or bacterial infection." (PMID 23941132, 2013).
Colorectal (3 papers, 2007 to 2021). "This study demonstrated CEACAM6, LGR5 and Wnt pathway suppression by CD151 silencing might occur through TGFβ1 regulation, offering a comprehensive view of CD151's roles in colorectal carcinogenesis." (PMID 33767593, 2021).
colonic polyps (2 papers, 2015 to 2023). "Mammalian CEACAM6 is also expressed in the alveolar and airway epithelial cells of the lungs under homeostatic conditions and is highly expressed in the gut only during intestinal disease." (PMID 37971273, 2023).
digestive system cancer (1 paper, 2021). A primary or metastatic malignant neoplasm involving any part of the digestive system. "Additional studies on digestive system cancers found that CEACAM6 could promote invasion and metastasis through epithelial-to-mesenchymal transition (EMT) by activating the PI3K/AKT signalling pathway." (PMID 34663338, 2021).
hematologic malignancies (1 paper, 2020). "Aberrant CEACAM6 expression leads to the development of several solid tumors and hematologic malignancies." (PMID 32648688, 2020).
infectious disease (1 paper, 2013). A disorder directly resulting from the presence and activity of a microbial, viral, or parasitic agent in humans. "Moreover, a low level of CEACAM6 protein expression has been noted in a variety of normal human tissues, including granulocytes and epithelia from various organs and this expression is also associated with infectious diseases." (PMID 23251258, 2013).
inflammation (1 paper, 2025). Aberrant reaction of the microcirculation characterized by movement of fluid and leukocytes from the blood into extravascular tissues. "Elevated levels of CEACAM6 have been associated with chronic inflammation and could serve as a more specific marker for immune dysregulation in UC compared to serum oncostatin M. CX3CL1, as a chemokine involved in immune cell trafficking, plays a crucial role in gastrointestinal mucosal immunity." (PMID 40115777, 2025).
CEACAM6 also shares sentences with these, for which no sentence is quoted: leukemia (4 papers); metastatic cancer (2); osteosarcoma (2); psoriasis (2); serous carcinomas of the ovary (2); small cell carcinoma (2); acute leukemia (1); acute myeloid leukemia (1); Anxiety (1); atypical ductal hyperplasia of the breast (1); B-cell acute lymphoblastic leukemia (1); benign tumors (1); biliary atresia (1); bronchopulmonary dysplasia (1); colon adenoma (1); colonic dysplasia (1); colorectal adenoma (1); diabetes (1); E. coli infection (1); endometrial cancer (1); epilepsy (1); esophageal cancer (1); gallbladder cancer (1); gallstones (1); gastroenteritis (1); gastrointestinal tumors (1); giant cell tumor (1); giant cell tumors of the bone (1); glioblastoma (1); Granuloma (1).
A further 28 diseases each share a sentence with CEACAM6 in 1 paper.